FBXO16 (F-box protein 16)
Description:
Substrate recognition component of an SCF (SKP1-CUL1-F-box protein) E3 ubiquitin-protein ligase complex that mediates the ubiquitination and subsequent proteasomal degradation of target proteins. Functions as a putative tumor suppressor by targeting nuclear beta-catenin/CTNNB1 for degradation independently of upstream activating signals, thereby inhibiting epithelial-to-mesenchymal transition. Controls the ubiquitination and degradation of hnRNPL. Negatively regulates NF-kappa-B signaling by mediating the polyubiquitination and degradation of RELA. Inhibits autophagy by promoting 'Lys-48'-linked polyubiquitination of the serine/threonine-protein kinase ULK1.
Synonyms: FBX16
Tractability: Antibody: the Human Protein Atlas places it where antibodies can reach.
Gene: Protein-coding gene on chromosome 8 (28,348,287 to 28,490,278, reverse strand). Ensembl gene ENSG00000214050.
Subcellular location (Human Protein Atlas): Cytosol; Nucleoplasm; Plasma membrane; Vesicles
Gene Ontology:
Molecular function: protein binding
Biological process: SCF-dependent proteasomal ubiquitin-dependent protein catabolic process
Cellular component: SCF ubiquitin ligase complex
Genetic constraint (gnomAD): Loss-of-function variants: 24 observed, 34.93 expected, observed/expected ratio (o/e) 0.69, 90% interval 0.5 to 0.97. The upper end of that interval is the gene's LOEUF score, 0.97, which puts it in group 4 of 6, group 1 being the genes least tolerant of losing a copy. Missense variants: 318 observed, 318.99 expected, observed/expected ratio (o/e) 1, 90% interval 0.91 to 1.09. Synonymous variants: 119 observed, 107.94 expected, observed/expected ratio (o/e) 1.1, 90% interval 0.95 to 1.28.
Homologues: Orthologues: macaque FBXO16 (94% identical), chimpanzee FBXO16 (91% identical), pig FBXO16 (87% identical), rabbit FBXO16 (85% identical), mouse Fbxo16 (85% identical), rat Fbxo16 (85% identical), dog FBXO16 (83% identical), guinea pig FBXO16 (78% identical), zebrafish fbxo16 (52% identical). Paralogues in human: FBXW7 (14% identical), WDR49 (14% identical), TRAF7 (12% identical), WDR64 (12% identical), FBXW9 (11% identical), WDR86 (11% identical), EFCAB8 (10% identical), FBXW12 (10% identical), BTRC (10% identical), FBXW11 (10% identical), WDR54 (8% identical), PAAF1 (7% identical), and 2 more.
Diseases named in the same sentence as FBXO16 in open-access papers:
FBXO16 is named in the same sentence as 7 diseases in open-access papers, as found by Europe PMC text mining. Sharing a sentence is not in itself a finding about the gene and the disease. The quoted sentences say what the papers report.
ovarian carcinoma (5 papers, 2021 to 2024). A malignant neoplasm originating from the surface ovarian epithelium. "All these results indicated that FBXO16 deficiency increased ovarian cancer cell malignant behavior in vitro." (PMID 34333526, 2021). "Failure to degrade hnRNPL promoted ovarian cancer cell proliferation in vitro and tumor growth vivo, phenocopying the deficiency of FBXO16 in ovarian cancer." (PMID 34333526, 2021). "Depletion of hnRNPL is sufficient to inactive multiple oncogenic signaling regulated by FBXO16 and prevent the malignant behavior of ovarian cancer cells caused by FBXO16 deficiency." (PMID 34333526, 2021). "More importantly, stable expressing a hnRNPLΔRRM3 mutant that cannot be recognized and degraded by FBXO16 phenocopied FBXO16 deficiency in ovarian cancer cells, indicating FBXO16 promotes the proliferation and invasion of ovarian cancer cells mainly via hnRNPL degradation." (PMID 34333526, 2021). "Furthermore, in vivo, malignant behavior of FBXO16 deficiency in ovarian cancer cells was determined in a xenograft mouse model." (PMID 34333526, 2021). "FBXO16 has been identified as a potential tumor suppressor in various cancer types, including ovarian cancer." (PMID 37958970, 2023). "ShRNA-mediated FBXO16 stable knockdown promoted ovarian cancer cell proliferation, clonogenic survival, and cell invasion." (PMID 34333526, 2021). "Silencing or depleting FBXO16 significantly enhanced ovarian cancer cell proliferation, clonogenic survival, and cell invasion by activating multiple oncogenic pathways." (PMID 34333526, 2021). "Together, these results suggest FBXO16 controls the ubiquitination and degradation of hnRNPL in ovarian cancer." (PMID 34333526, 2021). "TCGA database showed that FBXO16 mRNA expression was significantly increased in ovarian cancer tissues compared with normal ovarian tissues." (PMID 34333526, 2021). "To investigate how FBXO16 affects the oncogenic property of ovarian cancer, we conducted gene set enrichment analysis (GSEA) of the RNA-seq data of 426 ovarian cancer samples from TCGA." (PMID 34333526, 2021). "As expected, the depletion of FBXO16 dramatically enhanced the proliferation of ovarian cancer cell in vivo." (PMID 34333526, 2021). "qRT-PCR showed that both sh-FBXO16-1 and sh-FBXO16-3 displayed the most effective knockdown efficiency among these shRNAs we tested, inducing about 70–90% FBXO16 mRNA down-regulation in all ovarian cancer cell lines." (PMID 34333526, 2021). "In summary, our study found that FBXO16 is overexpressed in ovarian cancer tissues and cell lines, whereas high FBXO16 mRNA levels are significantly associated with relatively better prognosis." (PMID 34333526, 2021). "Here we discover FBXO16, an E3 ubiquitin ligase, to be a tumor suppressor in ovarian cancer, and patients with the relatively high expression level of FBXO16 have a better prognosis." (PMID 34333526, 2021). "In these differentially expressed FBPs, FBXL16 is the highest expressed FBP in ovarian cancer tissues, followed by FBXO16." (PMID 34333526, 2021). "Using four independent shRNA sequences targeting different regions of FBXO16 mRNA and three ovarian cancer cell lines with relatively high FBXO16 mRNA levels (A2780, OVCAR8, and SKOV3), we were able to achieve significant down-regulation levels of FBXO16 mRNA." (PMID 34333526, 2021). "Given the critical roles of these cancer-promoting pathways in ovarian cancer, their abnormal activation reveals the biological function of FBXO16." (PMID 34333526, 2021). "Here, we report that FBXO16 is overexpressed in ovarian cancer and has potent tumor-suppressive effect by targeting a heterogeneous nuclear ribonucleoprotein for ubiquitination dependent degradation." (PMID 34333526, 2021). "FBXO16 was able to suppress the proliferation, clonogenic survival, and cell invasion of ovarian cancer cells by mediating hnRNPL degradation and failure to destruct hnRNPL caused uncontrol malignant behavior of ovarian cancer cells." (PMID 34333526, 2021).
ovarian carcinoma (continued). "Together, these data indicate that FBXO16 is over-expressed in ovarian cancer, and the expression of FBXO16 can be used as a potential prognostic marker for ovarian cancer patients." (PMID 34333526, 2021). "To further investigate the biological function of FBXO16 in ovarian cancer, we used lentiviral-based short hairpin RNA (shRNA) to target the mRNA expression of FBXO16 in ovarian cancer cell lines." (PMID 34333526, 2021). "Altogether, our study highlights a pivotal role of the FBXO16-hnRNPL axis in controlling the proliferation, survival, and invasion of ovarian cancer cells." (PMID 34333526, 2021). "The protein levels of hnRNPL, but not its mRNA levels, were significantly increased in FBXO16 silenced or depleted ovarian cancer cells, suggesting the regulation of hnRNPL by FBXO16 occurs at the post-transcriptional level." (PMID 34333526, 2021). "In addition, given the tumor suppressor role of FBXO16 in ovarian cancer, how FBXO16 mRNA is upregulated needs further investigation." (PMID 34333526, 2021). "It will be interested to investigate whether the FBXO16/hnRNPL axis also regulates the stability of Bcl-2 mRNA in ovarian cancer in the future." (PMID 34333526, 2021). "Indeed, FBXO16 plays a critical role in the regulation of the proliferation, clonogenic survival, and cell invasion ability of ovarian cancer cells in a manner dependent on its E3 ligase activity." (PMID 34333526, 2021). "GSEA revealed that the expression of FBXO16 is negatively correlated with various cancer-promoting signaling pathways, suggesting that FBXO16 may regulate these signaling pathways in ovarian cancer." (PMID 34333526, 2021). "To investigate whether hnRNPL mediates the role of FBXO16 in ovarian cancer, we further used the CRISPR/Cas9 system to knockdown hnRNPL and FBXO16 individually or simultaneously." (PMID 34333526, 2021). "We found that ovarian cancer patients with relatively high expression levels of FBXO16 have a better prognosis, suggesting that FBXO16 may play a tumor suppressor role in ovarian cancer." (PMID 34333526, 2021). "As FBXO16 can modulate and negatively correlate with many cellular signaling pathways in ovarian cancer cells, we hypothesize that FBXO16 could also regulate the polyubiquitination and degradation of other substrates, which requires further investigation to clarify." (PMID 34333526, 2021). "We next performed Immunohistochemistry (IHC) analysis to evaluate the potential association between FBXO16 and hnRNPL in 68 human ovarian cancer specimens and a negative correlation between FBXO16 and hnRNPL proteins was observed in those ovarian cancer specimens (χ2 = 14.81, P < 0.001)." (PMID 34333526, 2021). "DCAF10, FBXO16, PTPN2, SAYSD1, and ZNF426 are genes that confer protection to ovarian cancer patients, with their heightened expression correlating with improved survival rates." (PMID 37958970, 2023). "In this study, FBXO16 was identified as an adaptor protein of a SCF E3 ligase complex that regulates the ubiquitination and degradation of its substrate protein hnRNPL in ovarian cancer." (PMID 34333526, 2021). "F-box protein 16 (FBXO16) is an E3 ubiquitin ligase that can promote ubiquitin-proteasome degradation of L protein through ubiquitination of HNRNP L, and ultimately prevent the malignant development of ovarian cancer." (PMID 39366930, 2024).
breast carcinoma (3 papers, 2019 to 2023). "In the realm of breast cancer, FBXO16 holds potential as a clinical target and prognostic biomarker across diverse molecular subtypes." (PMID 37958970, 2023). "In luminal-types breast carcinoma, FBXO16 was inclined to over-express in luminal A and B groups and FBXO28 was a potential up-regulated biomarker of luminal B groups." (PMID 33622332, 2021). "Immunohistochemical analysis demonstrated a significant converse correlation of FBXO16 and β‐catenin expression with increased levels of β‐catenin and concomitant attenuation of FBXO16 in higher grades of breast cancer patient samples." (PMID 30714168, 2019). "It is further supported by a database of breast cancer patient samples coupling overall survival of the patient with higher levels of FBXO16." (PMID 30714168, 2019). "A significant inverse relationship of FBXO16 and β‐catenin in breast cancer patient samples was observed." (PMID 30714168, 2019). "For a clinical perspective, we then checked the correlation of FBXO16 and β‐catenin expression in the breast cancer patient samples." (PMID 30714168, 2019). "β‐Catenin is known to be involved in progression and metastasis of breast cancer, and we were intrigued to draw up a correlation between β‐catenin and FBXO16 in the context of breast cancer." (PMID 30714168, 2019). "It has been suggested that FBXO16 might serve as a clinical target for therapeutic intervention, particularly in breast cancer, where its role as a prognostic biomarker across distinct molecular subtypes is being explored." (PMID 37958970, 2023). "Furthermore, FBXO16 and β‐catenin share an inverse correlation of cellular expression in clinical breast cancer patient samples." (PMID 30714168, 2019). "Interestingly, the expression of FBXO16 and β‐catenin is conversely correlated in breast cancer patient samples, with the attenuation of FBXO16 expression with cancer progression." (PMID 30714168, 2019). "Depletion of FBXO16 resulted in increased malignancy because of aberrant nuclear accumulation of β‐catenin, emphasizing that elevated levels of FBXO16 in higher grades of breast cancer could be therapeutically beneficial to abrogate the β‐catenin driven malignancy." (PMID 30714168, 2019).
glioblastoma (2 papers, 2021 to 2022). The most malignant astrocytic tumor (WHO grade IV). "For instance, FBXO16 is discovered as a tumor suppressor in glioblastoma by targeting Wnt signaling pathway." (PMID 34926132, 2021).
autoimmune disease (1 paper, 2025). A disorder resulting from loss of function or tissue destruction of an organ or multiple organs, arising from humoral or cellular immune responses of the individual to their own tissue constituents. "We therefore speculate that Fbxo16-deficiency in humans may cause autoimmune diseases and that the Fbxo16/PDLIM2-mediated pathway to terminate NF-κB activation could be the molecular tool for the development of the new therapy of these diseases." (PMID 40529355, 2025).
glioma (1 paper, 2021). A benign or malignant brain and spinal cord tumor that arises from glial cells (astrocytes, oligodendrocytes, ependymal cells). "FBXO16 expression in gliomas is low, so it would be appropriate to evaluate how this expression is controlled in this type of cancer to eventually use the FBXO16 → β-catenin pathway as a therapeutic route." (PMID 33665742, 2021).
tumor (8 papers, 2019 to 2025). "Deficiency of FBXO16 results in elevated β-catenin levels, subsequently fostering certain processes, such as cancer cell invasion, tumor proliferation, and epithelial–mesenchymal transition." (PMID 37958970, 2023). "Loss of FBXO16 could lead to increased β-catenin levels, contributing to cancer cell invasion, tumor growth, and metastasis." (PMID 37958970, 2023). "The FBXO16 gene functions as a tumor suppressor, and recent studies have shown that the FBXO16 gene mediates the degradation of NF-κB p65 subunits, thereby inhibiting inflammatory responses in dendritic cells." (PMID 41007947, 2025). "Forced expression of Fbxo16 in tumor cell lines inhibited cell growth, whereas knockdown of Fbxo16 in these cells resulted in increased β-catenin and hnRNPL protein levels and enhanced tumor cell proliferation." (PMID 40529355, 2025). "The high expression of FBXO16 can inactivate a variety of oncogenic signaling pathways and thus help to inhibit excessive tumor proliferation." (PMID 34333526, 2021). "In one sense, FBXO16 is a putative tumor suppressor that suppresses the growth, migration and invasion of cancer cells." (PMID 33622332, 2021). "In summary, we propose that FBXO16 functions as a putative tumor suppressor by forming an SCFFBXO16 complex that targets nuclear β‐catenin in a unique manner for ubiquitination and subsequent proteasomal degradation to prevent malignancy." (PMID 30714168, 2019). "We show that FBXO16 functions as a putative tumor suppressor by abrogating the function of nuclear β‐catenin." (PMID 30714168, 2019). "Our results show that FBXO16 is a putative tumor suppressor that suppresses the growth, migration, invasion of cancer cells, and EMT by directing the proteasomal degradation of nuclear β‐catenin." (PMID 30714168, 2019). "Regarding Fbxo16, previous reports showed that it mediates polyubiquitination and degradation of β-catenin and heterogeneous nuclear ribonucleoprotein L (hnRNPL), both of which regulate signaling pathways leading to cell proliferation and tumor progression." (PMID 40529355, 2025). "FBXO16, an F-box protein, has garnered attention for its tumor-suppressive properties." (PMID 37958970, 2023). "Collectively, our findings suggested that FBXO16 might function as a putative tumor suppressor by limiting nuclear β‐catenin activity." (PMID 30714168, 2019). "Our results demonstrated that tumor growth was markedly increased following depletion of FBXO16." (PMID 30714168, 2019). "Therefore, depletion of FBXO16 leads to increased levels of β‐catenin, which then promotes cell invasion, tumor growth, and EMT of cancer cells." (PMID 30714168, 2019). "In this study, we show that F‐box protein 16 (FBXO16) is a putative tumor suppressor." (PMID 30714168, 2019). "Collectively, our findings suggested that FBXO16 may function as a putative tumor suppressor by limiting the activity of nuclear β‐catenin." (PMID 30714168, 2019). "Moreover, the immunohistochemistry (IHC) analysis for Ki67 staining, a cell proliferation marker, showed that FBXO16 deletion tumor tissues had increased Ki67 expression compared with FBXO16 WT tumor tissues, suggesting a tumor suppressor function of FBXO16 in vivo." (PMID 34333526, 2021). "Thus, FBXO16 is the first F‐box protein that facilitates degradation of nuclear β‐catenin, thereby inhibiting the cancer cell proliferation, migration, invasion in vitro, and tumor formation in NOD‐SCID mice." (PMID 30714168, 2019). "Re-expression of wild-type FBXO16 (FBXO16 WT), but not the F-box domain deleted mutant (FBXO16 ΔF), can impair the proliferation, clonogenic survival, and cell invasion ability caused by FBXO16 deletion, indicating that the tumor inhibition effect of FBXO16 depends on its E3 ligase activity." (PMID 34333526, 2021).
cancer (6 papers, 2019 to 2025). A tumor composed of atypical neoplastic, often pleomorphic cells that invade other tissues. "Notably, the association of higher Fbxo16 expression with better prognosis in cancer patients and the attenuated Fbxo16 expression in higher-grade cancer samples were observed in a human cancer database." (PMID 40529355, 2025). "Next, we examined cancer cell line growth following depletion of FBXO16 in MCF7 cells." (PMID 30714168, 2019). "Here, we decipher the function of FBXO16, an F‐box protein, in cancer." (PMID 30714168, 2019). "Fbxo16 could therefore acts as the substrate-recognizing receptor for several proteins involved in cell proliferation, including β-catenin, hnRNPL and NF-κB p65, promotes their degradation and prevents cancer progression." (PMID 40529355, 2025). "Thus, the activation of FBXO16 expression could be a novel therapeutic strategy in preventing cancers expressing the aberrant nuclear accumulation of β‐catenin." (PMID 30714168, 2019). "Hence, we performed a series of experiments to check whether FBXO16 has any role in cancer cell proliferation, either by its overexpression/depletion." (PMID 30714168, 2019).